EGFR (epidermal growth factor receptor)
Diseases named in the same sentence as EGFR in open-access papers (continued):
Sharing a sentence is not in itself a finding about the gene and the disease.
ovarian carcinoma (continued). "We report here on the successful use of functionalized nanohydrogels for the targeted delivery of siRNA against EGFR (epidermal growth factor receptor) in an ovarian cancer mouse model and the consequent inhibition of tumor growth and enhancement of cisplatin chemotherapy." (PMID 27819259, 2016). "For instance, overexpression of YAP1 could contribute to progression and poor prognosis of NSCLC, while knockdown of YAP1 sensitized ovarian cancer cells to cisplatin, erlotinib (EGFR Tyrosine kinase inhibitor) and S12 (survivin inhibitor)." (PMID 26716514, 2016). "Similarly, it was reported that overexpression of FSHR in OSE cells led to an increase in expression of proteins involved in ovarian cancer development such as EGFR, c-myc, and HER2/neu." (PMID 26635885, 2016). "Our findings showed that ovarian cancer cells could be induced to secrete MMP-9 in response to EGFR activation by physiological levels of HB-EGF." (PMID 27888810, 2016). "Estrogen and G-1 induce ovarian cancer cell growth responses via EGFR-MAPK signaling pathways." (PMID 27314054, 2016). "As a consequence, EGFR has been a subject of investigation for targeted therapies, with monoclonal antibodies and small-molecule tyrosine kinase inhibitors, exploring it as a potential therapeutic agent in ovarian carcinoma." (PMID 26870997, 2016). "In ovarian cancers, elevated expression of EGFR is correlated with poor prognosis." (PMID 27129169, 2016). "The reported findings and our results may at least partially explain the synergistic effects between monensin and EGFR inhibitors in suppressing cell proliferation of ovarian cancer cells." (PMID 26639992, 2015). "Thus, anticancer agents that target EGFR or its downstream signaling pathways hold great promise for treatment of ovarian cancer." (PMID 26489763, 2015). "Taken together, we hypothesized that the cisplatin induced activation of the EGFR contributes to the development of platinum resistance in ovarian cancer cells through regulation of DNMT activity and DNA methylation." (PMID 26351843, 2015). "It remains to be addressed whether ovarian cancer patients could benefit from targeting EGFR signaling." (PMID 25928246, 2015). "However, inhibition of EGFR signaling in patients with recurrent ovarian cancer has been disappointing." (PMID 25928246, 2015). "To test our hypothesis, we evaluated activation of the EGFR, downstream signaling pathways and DNA methyltransferase activity in ovarian cancer cells in response to physiologically relevant doses of cisplatin." (PMID 26351843, 2015). "For other tumor types, such as ovarian cancer, the nuclear EGFR expression shows prognostic value." (PMID 25991665, 2015). "This study may provide a strategy to improve clinical benefit of targeting EGFR pathway in ovarian cancer patients." (PMID 25928246, 2015). "This work provides a targetable, mechanistic link between cisplatin treatment and platinum resistance that may repurpose EGFR inhibitors in ovarian cancer." (PMID 26351843, 2015). "The results provided in this report suggest that targeting LSD1 may be an effective approach for inhibiting the progression of ovarian cancer, particularly EGFR signaling-dependent progression." (PMID 26489763, 2015). "EGFR is often overexpressed in ovarian cancer and correlates with poor prognosis." (PMID 26121572, 2015). "In this study, we investigated the mechanism for the limited activity of the EGFR inhibitor, gefitinib, in ovarian cancer cells, and found that increased activity of STAT3 after gefitinib treatment could partially explain the gefitinib resistance." (PMID 25928246, 2015). "Elevated EGFR expression results in poor prognosis in lung, breast and ovarian cancer." (PMID 25776829, 2015). "Identification of tangible targets, such as the EGFR, responsible for the development of platinum resistance could provide a means to make platinum therapy more effective for ovarian cancer and other cancers." (PMID 26351843, 2015).
ovarian carcinoma (continued). "Here, we investigated the mechanisms of crosstalk between PAFR and EGFR signaling in ovarian cancer cells to further determine whether the interaction between PAFR and EGFR synergistic contribute to the progression of ovarian cancer." (PMID 25261977, 2014). "In addition to cell growth, we examined the effects on cell invasion of combined PAFR and EGFR targeting in ovarian cancer cells." (PMID 24886678, 2014). "Overexpression of EGFR is common in cancers, including 35-70% of ovarian cancers." (PMID 24721622, 2014). "Lonidamine and Paclitaxel dual loaded PLGA/PEG/EGFR-peptide targeted nanoparticles at 1 μM paclitaxel/10 μM lonidamine dose revealed <10% cell viability for all hypoxic cell lines and <5% cell viability for all normoxic cell lines overexpressing EGFR in human breast and ovarian cancer cell lines." (PMID 25071577, 2014). "The aim of this study was to determine whether PAF transactivates EGFR in ovarian cancer cells, examine the involvement of the PAFR in this process, and elucidate the intracellular signaling mechanisms required for transactivation." (PMID 25261977, 2014). "In addition, earlier experiments from our group have shown that the activation of PAFR has pleiotropic effects on tyrosine phospho-EGFR/Src/Paxillin in ovarian cancer." (PMID 24886678, 2014). "Targeting EGFR has a moderate effect in ovarian cancer, probably due to collateral escaping mechanisms, which could be avoidable by targeting downstream members of the oncogenic pathway." (PMID 25408231, 2014). "Our work with EGFR pathway in ovarian cancer led us to investigate whether the EGFR and its downstream signaling pathways were involved in the reversal of EMT by miR-7." (PMID 24816687, 2014). "PAF has the potential to transactivate EGFR in ovarian cancer cells." (PMID 24721622, 2014). "In addition, HE4 was found to promote the invasion and metastasis of ovarian cancer cells via the EGFR/MAPK pathway." (PMID 25362534, 2014). "Overexpression of EGFR and inhibition of proliferation has been observed in cisplatin-treated ovarian carcinoma cells, and these molecular changes were hypothesized to be an escape mechanism of tumor cells." (PMID 25216514, 2014). "We next investigated whether the PAF-receptor (PAFR) is involved in the transactivation of EGFR in ovarian cancer cells." (PMID 25261977, 2014). "Indeed, it has been reported that epidermal growth factor (EGF) receptor (EGFR) is frequently elevated in epithelial ovarian cancer, and that E-cadherin expression is often reduced in the advanced stages of the disease." (PMID 26932374, 2014). "Approximately 70% of epithelial ovarian cancer (EOC) express activated EGFR." (PMID 24816687, 2014). "Furthermore, we show that miR-7 reverses EMT through AKT/ERK1/2 inactivation by targeting EGFR in EOC, which provides a novel insight into the mechanisms underlying metastasis of ovarian cancer." (PMID 24816687, 2014). "Additionally, EGFR expression was higher in normal tissues of BRCA1-mutated patients, and was further increased in cancer tissues; EGFR levels were also significantly elevated in ovarian cancer with promoter hypermethylation-mediated inactivation of BRCA1." (PMID 24321281, 2013). "Notably, the expression levels of EGFR were markedly increased (P < 0.05), along with a hypermethylated promoter-mediated BRCA1 deficiency in ovarian cancer (P < 0.05)." (PMID 24321281, 2013). "BRCA1 knockdown was an effective way to activate EGFR expression in ovarian cancer cells." (PMID 24321281, 2013). "Over-expression of the EGFR gene is frequent in ovarian cancers." (PMID 24587967, 2013). "Epidermal growth factor receptor (EGFR) is expressed in 70% of ovarian carcinomas." (PMID 23644885, 2013).
ovarian carcinoma (continued). "A primary finding of this study is that CXCR2-driven cancer progression involves upregulation of its own ligands such as CXCL1 and CXCL2 by potentiating NF-κB activation via EGFR-transactivated Akt signaling followed by accelerated ovarian cancer cell proliferation, migration and invasion." (PMID 24376747, 2013). "Hence, the induced expression of EGFR was likely to be the result of a complex interaction of special factors in ovarian cancer cells." (PMID 24321281, 2013). "Interestingly, we observed that the knockdown of BRCA1 was an effective way to induce an increase of EGFR levels in SKOV3 and non-BRCA1-mutated ovarian cancer cells." (PMID 24321281, 2013). "However, to date, there have been few reports about the interactions between BRCA1 and EGFR in ovarian cancer." (PMID 24321281, 2013). "In addition, the epidermal growth factor receptor (EGFR) is frequently overexpressed in high-grade ovarian cancer, which likely aggravates cancer progression." (PMID 23800251, 2013). "However, the authors stated that EGFR expression in combination with GPER-1 predicts lower survival in patients with ovarian cancer." (PMID 23849542, 2013). "The aim of this study was first to investigate the combined inhibition of EGFR by Cetuximab and the tyrosine kinase inhibitors Erlotinib, Gefitinib and Vandetanib in an ascites-derived primary cell culture and in a variety of ovarian cancer cell lines with different EGFR-expression." (PMID 23109896, 2012). "In this study, we evaluated the targeting efficiency of anti-EGFR-liposomes to ovarian carcinoma." (PMID 22844475, 2012). "To understand the effect of MT19c on EGFR and its downstream signaling cascade in ovarian cancer, we investigated the effect of MT19c on EGFR and PI-3kinase activity in SKOV-3 cells by western blot analysis, microscopy and an in vitro PI-3kinase activity assay." (PMID 22509304, 2012). "We also examined whether GPR30 signaling activates the EGFR-Akt pathway in an ovarian cancer cell line (Caov-3) by a Western blotting analysis." (PMID 23163984, 2012). "In the present study, the molecular markers of progenitors in cells isolated from ascites and tumor tissues of patients with advanced or recurrent ovarian cancer were the highly expressed EGFR and Flt-4 (VEGF receptor), which are important during tumor angiogenesis and metastasis." (PMID 22330345, 2012). "The present findings are relevant to the results obtained in a previous study in which we found that atrazine, another environmental contaminant, triggered estrogen-like activity through the GPER/EGFR/ERK transduction pathway in hormone-sensitive ovarian cancer cells." (PMID 22552965, 2012). "In addition, the same group has also shown that there was a strong correlation between E2F3a expression and activated EGFR in ovarian cancer specimens and that E2F3a was a key player in EGFR driven cell proliferation." (PMID 22629428, 2012). "Despite the existence of anti-EGFR-resistance in ovarian cancer cetuximab might exert immune modulating effects via antibody-dependent cellular cytotoxicity (ADCC) and might enhance antitumoural activity in a NK cell-based immunotherapeutic approach." (PMID 23036052, 2012). "In ovarian cancers, mutant or isoforms of EGFR RTKs transactivate signaling transduction cascades such as PI3K/AKT and Ras/Raf/MEK/MAPK/ERK that result in diverse effects, including cell proliferation, dedifferentiation, adhesion, migration, invasion, angiogenesis, and apoptosis evasion." (PMID 22481932, 2012). "This might suggest that GPR30 is involved in a signaling cascade that is transduced via the EGFR, which leads to a poor prognosis for ovarian cancer, since the phosphorylation of Akt via the EGFR is key to the development and/or progression of ovarian cancer." (PMID 23163984, 2012). "The EGFR-expression of these ovarian cancer cell lines was analysed by western blotting." (PMID 23036052, 2012). "The overexpression of EGFR in ovarian cancer correlates with poor prognosis." (PMID 22860069, 2012).
ovarian carcinoma (continued). "Activation of various tyrosine kinases including EGFR is important in ovarian cancer pathogenesis." (PMID 22952709, 2012). "However, PstS-1 did not directly influence purified NK cells and did also not affect natural and antibody-dependent cellular cytotoxicity directed against EGFR-positive ovarian cancer cells, even in presence of monocytes." (PMID 23036052, 2012). "Interestingly, our results also revealed a dramatic reduction in the protein expression of EGFR in ovarian cancer cells treated with PEITC." (PMID 22952709, 2012). "Additionally, oncolytic viruses engineered to deliver anti-EGFR antibodies to intraperitoneal ovarian cancer cells show great potential as a future gene therapeutic focus." (PMID 22481932, 2012). "Thereby, EGFR might be a suitable target since EGFR is overexpressed in up to 70% of ovarian cancer and anti-EGFR-antibodies like cetuximab and panitumumab are tested in clinical setting." (PMID 23036052, 2012). "Porcile found that CXCL12 induced EGFR phosphorylation in ovarian cancer cells." (PMID 22848341, 2012). "Although the function of EGFR signaling in cultured ovarian cancer cells has been studied, its function in the borderline tumors and in LGC is still unknown due to the lack of a suitable in vitro model." (PMID 22479527, 2012). "The epidermal growth factor receptor (EGFR) family is commonly overexpressed in ovarian cancer and has been associated with a negative prognosis; however, limited efficacy has been observed with molecules targeted to the EGFR pathway." (PMID 22481926, 2012). "Moreover, Jeong KJ and colleagues demonstrated that lysophosphatidic acid receptor, LPA2 and Gi/Src transactivation to EGFR are responsible for COX-2 expression in ovarian cancer cells." (PMID 21756326, 2011). "In this study, we investigate the EGFR protein expression using a novel antibody against the intracellular domain of the receptor in a cohort of primary invasive ovarian carcinomas as well as human ovarian cancer cell lines." (PMID 21756326, 2011). "Furthermore, we evaluated EGFR expression in ten ovarian cancer cell lines and incubated cancer cells with Leptomycin B, a CRM1 specific inhibitor." (PMID 21756326, 2011). "Erlotinib (Tarceva, OSI Pharmaceuticals, Long Island, NY, USA), another small molecule inhibitor of EGFR, demonstrated a 6% partial response rate in a multicentre phase II trial with EGFR-positive ovarian cancer patients with taxane- and/or platinum-refractory or -resistant disease." (PMID 21364581, 2011). "So far, the application of anti-EGFR therapy in ovarian cancer has been shown only limited efficacy; therefore further studies will be needed to investigate whether (membranous) EGFR is also predictive for benefit from EGFR targeted therapies." (PMID 21756326, 2011). "Our results suggest that the EGFR/COX-2/CRM1 interaction might be involved in progression of ovarian cancer and patient prognosis." (PMID 21756326, 2011). "In ovarian carcinomas different results exist concerning EGFR expression and disease outcome." (PMID 21756326, 2011). "Further, the role of EGFR in different ovarian cancer histotypes should be examined." (PMID 20037743, 2010). "EGFR is overexpressed in a high proportion of ovarian carcinomas." (PMID 24281034, 2010). "Based on these findings, we sought to determine if siRNA against EGFR could be selectively delivered to ovarian cancer cells using a nanoparticle carrier." (PMID 20064265, 2010). "To date, clinical studies using EGFR antagonists in ovarian cancer have shown limited efficacy." (PMID 20037743, 2010). "The expression of EGFR and Her-2 has been extensively studied in ovarian cancer." (PMID 20885926, 2010). "While the number of samples analyzed in depth is increasing, this number is still relatively small; whether the profile of EGFR-positive ovarian cancers is different from that of other prominent molecular markers is unknown." (PMID 20037743, 2010).
ovarian carcinoma (continued). "By the in vitro studies in human ovarian cancer cells, EGFR and its downstream effectors may be activated directly or indirectly by numerous other signaling molecules." (PMID 20037743, 2010). "Based on these reports and the emergence of numerous potential EGFR-mediated signaling proteins of interest in ovarian cancers, determination of which proteins play crucial roles in ovarian tumors might prove to be a challenging process." (PMID 20037743, 2010). "Among patented mAbs directed towards EGFR that are not yet in clinical use, one has been proposed for use in ovarian cancer (patent number WO2005010151); however, as it is directed against deletion mutants of EGFR (particularly EGFRvIII), its use in ovarian cancer is likely to be limited." (PMID 20037743, 2010). "More comprehensive, systematic, and well-defined approaches are needed to dissect the roles that EGFR plays in the complex signaling processes in ovarian cancer as well as to identify biomarkers that can accurately predict sensitivity toward EGFR-targeted therapeutic agents." (PMID 20037743, 2010). "This complex pattern of EGFR family activation could in part explain the poor rate of response to EGFR inhibition in ovarian cancer." (PMID 20037743, 2010). "While 2 of 20 NSCLC samples displayed an activating deletion in exon 19 (consistent with previous reports), no EGFR mutations were detected in the ovarian carcinomas." (PMID 20037743, 2010). "This, as yet, has not been explored with anti-EGFR therapy in ovarian cancers although the KRAS pathway is implicated in ovarian tumorigenesis particularly in low grade serous and mucinous carcinomas." (PMID 24281034, 2010). "In addition, it was also demonstrated that CXCL12 effects on ovarian cancer cell lines are mediated by EGFR transactivation through a mechanism involving the activity of cytosolic tyrosine kinases, belonging to the c-Src family." (PMID 20049170, 2010). "It has been shown that EGFR mutations do not play a role in ovarian cancer, while KRAS mutations are very well documented." (PMID 19358724, 2009). "Because ovarian cancer patients are also being considered for treatment with EGFR-targeting substances, and as clinical trials are already conducted, it is crucial to know whether patients harbouring a ras mutation may benefit from such therapy." (PMID 19358724, 2009). "We studied the association between the increased levels of STAT3 activation and high-grade ovarian carcinomas, consistent with a role for STAT3 in the motile phenotype of ovarian cancer cells in response to direct activation by EGFR or indirectly through IL-6R." (PMID 19088723, 2009). "Therefore it is important to investigate the efficacy of EGFR inhibitors in (ovarian) cancer in patients prospectively selected for an altered gene status." (PMID 18182111, 2008). "Therefore, we examined the entire tyrosine kinase domain encoding exons (exons 18–24) of both EGFR and HER2-neu in a cohort of ovarian cancers." (PMID 18182111, 2008). "Genomic alteration of the HER2-neu and EGFR genes is frequent (25%) in ovarian cancer." (PMID 18182111, 2008). "Several of these pathways are activated in ovarian carcinoma as was shown for EGFR, PI3K or Akt." (PMID 15841084, 2005). "However, tyrosine phosphorylation of the EGFR in clinical specimens of ovarian cancer can be readily identified and it seems likely that those tumours in which activation is found represent the target population for these agents." (PMID 11875715, 2002). "Strategies targeting the EGFR may well have therapeutic potential in ovarian cancer as the receptor is frequently overexpressed in this disease and patients with tumours expressing high levels of EGFR tend to have a poor prognosis." (PMID 11875715, 2002). "Thus, targeting of EGFR, along with inhibition of p38 MAPK or DNA repair, may improve the efficacy of EGFR-mediated treatment in ovarian cancer." (PMID 40868085, 2025).